CDK7 (cyclin dependent kinase 7)
Diseases named in the same sentence as CDK7 in open-access papers (continued):
Sharing a sentence is not in itself a finding about the gene and the disease.
breast carcinoma (continued). "In conclusion, our results demonstrated that CDK7/10/13/19 expression is significantly higher in breast cancer than in normal breast tissues, both at the mRNA and protein levels." (PMID 33686962, 2021). "We demonstrated that GSDME deficiency facilitated breast cancer cell proliferation and colony formation while CDK7 inhibition impaired the ability of breast cancer proliferation and colony formation." (PMID 34490348, 2021). "We transfected breast cancer cells with CDK7 shRNA lentiviruses to verify the anti-tumor effect of CDK7 inhibition." (PMID 34490348, 2021). "The expression of CDK7/10/13/19 mRNAs in breast cancer tissues was significantly higher than in normal breast tissues." (PMID 33686962, 2021). "The effects of CDK7 inhibitors on breast cancer cells have been identified by measuring cell viability (Cell Counting Kit-8) and cell proliferation and calculating colony formation." (PMID 34109118, 2021). "Here, we show that inhibition of CDK7 efficiently decreases the mRNA levels of CCND1 in HE2iR breast cancer cells." (PMID 31462705, 2020). "To explore the role of CDK7 in breast cancer growth, we first examined the effects of THZ1 on breast cancer cell lines encompassing TNBC, ER+/HER2-, ER+/HER2+ and ER-/HER2+ subtypes over seven days of treatment." (PMID 32155786, 2020). "We first examined mRNA sequencing data from The Cancer Genome Atlas (TCGA) database for patients with breast cancer to assess the potential correlation between CDK7 and estrogen receptor alpha or 1 (ER1 or ER-α) levels." (PMID 32340192, 2020). "We also explored the effects of CDK7 inhibition on transcription to identify potential biomarkers of response to THZ1 across different subtypes of breast cancer." (PMID 32155786, 2020). "Here, we report that in a cohort of patients receiving tamoxifen as a hormonal therapy for breast cancer, patients with a high level of CDK7 had a lower survival rate than did those with low CDK7." (PMID 32340192, 2020). "In oestrogen receptor-positive (ER+) breast cancer, CDK7, cyclin H and MAT1 are overexpressed and are co-regulated at the mRNA level." (PMID 32385714, 2020). "We then ask if inhibition of CDK7 resensitizes breast cancer cells to lapatinib, a HER2-targeted agent commonly used in patients with HER2+ metastatic breast cancer." (PMID 31462705, 2020). "Additional animal models should be used with siRNA separately or combined with tamoxifen in sensitive and resistant cells, as well as different CDK7 inhibitors in other types of breast cancer to explore if it has any significant effect." (PMID 32340192, 2020). "In an effort to reconcile the various findings detailed above, we explored the therapeutic potential of CDK7 inhibition in a panel of breast cancer cell lines representing the major breast cancer subtypes." (PMID 32155786, 2020). "CDK7 is an essential gene in both ER-wild-type and ER-mutant breast cancer, and ER-mutant MCF7 cells, that are partially resistant to anti-oestrogens, are sensitive to CDK7 inhibition." (PMID 32385714, 2020). "Nar isolated from Thymus vulgaris upregulated pro-apoptotic markers, p18, p19, p21, Bax and Bak, and downregulated anti-apoptotic markers, Cdk4, Cdk6, Cdk7, and Bcl-2 in human colorectal and breast cancer cells leading to apoptosis." (PMID 33192517, 2020). "As ER is the key transcriptional driver of ER+ breast cancer and is activated by CDK7, CDK7 inhibitors have been assessed in combination with anti-oestrogens in this context." (PMID 32385714, 2020). "To further elucidate the effects of CDK7 inhibition in breast cancer, we profiled a panel of cell lines representing different breast cancer subtypes." (PMID 32155786, 2020). "CDK7 inhibition inhibits the growth of ESR1-mutant breast cancer and can overcome chemotherapy resistance in breast cancer." (PMID 31530935, 2020). "Here, we describe a novel treatment strategy that targets cyclin-dependent kinase 7 (CDK7) in HER2 inhibitor-resistant (HER2iR) breast cancer." (PMID 31462705, 2020).
breast carcinoma (continued). "In summary, our mechanistic studies provide evidence that CDK7 activates ER-α phosphorylation at Ser118 which enhances the transcription of MYC in ER+ breast cancer (pathway 1)." (PMID 32340192, 2020). "In the current study, we showed a correlation between CDK7 levels and ER-α expression in all breast cancers and in ER+ breast cancers in particular." (PMID 32340192, 2020). "To further investigate the effects of CDK7 inhibition on cell growth in different subtypes of breast cancer, we screened a panel of 13 breast cancer cell lines for response to THZ1 after 2 or 7 days of treatment." (PMID 32155786, 2020). "Previous studies have reported that the silencing of CDK7 expression via a number of methods suppresses the growth and proliferation of liver carcinoma, lymphoma, leukemia, intestinal carcinoma and breast cancer cells." (PMID 25411854, 2015). "CDK7/9 inhibitor in ER-positive breast cancer cells has showed to prevent activating phosphorylation of ER-α59." (PMID 25990212, 2015). "Given that CDK7 activates the main CDKs at different cell cycle transitions, it is possible to assume that the over expression of CDK7 also contributes to breast cancer cell proliferation." (PMID 23561625, 2013). "Currently, selective CDK7 inhibitors such as Q901, TY-2699a, XL-102, and SY-5609, are being explored as monotherapies or in combination with other drugs for treating advanced solid tumors, including breast cancer." (PMID 40949156, 2025). "However, although most reported functions of CSDE1 are cytoplasmic, it has been recently proposed that CSDE1 interacts with RNApol-II and CDK7 to promote transcription in breast cancer cells." (PMID 38396995, 2024). "In an examination of CDK7’s abundance within normal breast epithelium and a cohort of 12 breast cancer cell lines, immunoblotting analysis distinctly revealed elevated CDK7 protein expression within malignant counterparts as opposed to normal breast epithelium." (PMID 38605321, 2024). "Thus, our findings advocate for the strategic exploration of anti-CDK7 therapy as a promising avenue in breast cancer management." (PMID 38605321, 2024). "Interestingly, TNBC cells displayed heightened sensitivity to CDK7 inhibition when compared to HR+ breast cancer cells." (PMID 38605321, 2024). "The prognostic significance of CDK7 in breast cancer remains a matter of considerable debate." (PMID 38605321, 2024). "Furthermore, we synthesize the extant literature to provide a comprehensive overview of the advancement of CDK7-specific small-molecule inhibitors, encapsulating both preclinical and clinical findings in breast cancer contexts." (PMID 38605321, 2024). "Moreover, SY-1365, a highly selective CDK7 inhibitor, is currently used in clinical trials in patients with ovarian and breast cancer." (PMID 35514959, 2022). "Overexpression of CDK7 is commonly observed in a broad spectrum of human cancers for example breast cancer, hepatocellular carcinoma, gastric cancer, colorectal cancer, squamous cell carcinomas of the oral cavity, head and neck (HNSCC) and esophagus, as well as ovarian cancer." (PMID 36212402, 2022). "Thus far, accumulating studies have demonstrated that CDK7 is frequently overexpressed in diverse tumor tissues including gastric cancer, oral squamous cell carcinoma, and breast cancer." (PMID 34109118, 2021).
breast carcinoma (continued). "In addition, not only recent mRNA expression profiling but also immunohistochemistry studies have demonstrated that the expression of CDK7 in ER+ breast cancer was elevated." (PMID 34109118, 2021). "Our results suggest that CDK7/8/13 could be prognostic biomarkers for breast cancer patients and may offer valuable insights for the development of therapies targeting TA-CDKs in breast cancer." (PMID 33686962, 2021). "Survival analysis of breast cancer patients revealed that increased CDK8 expression was associated with inferior overall survival (OS), higher expression of CDK7 or CDK8 was associated with inferior relapse-free survival (RFS), but higher expression of CDK13 was associated with favorable RFS and OS." (PMID 33686962, 2021). "CDK14 has been shown to interact with other cyclins as well, such as cyclin B to activate the Wnt pathway in breast cancer, cyclin D3 to regulate cell cycle progression and proliferation in mammalian cells, and the CDK7/cyclin H complex to regulate proliferation and migration in esophageal cancer." (PMID 34571979, 2021). "Moreover, CDK7 inhibition has been shown to be effective in low concentrations in many cancer types, including leukemia, ovarian cancer, and colon cancer, which makes CDK7 inhibitors good candidates for use as adjuvant breast cancer treatment." (PMID 32340192, 2020). "Our findings identify CDK7 as a possible therapeutic target for breast cancer whether it is sensitive or resistant to tamoxifen therapy." (PMID 32340192, 2020). "In contrast to negative prognostic correlations of CDK7 RNA levels, a study that used immunohistochemistry-based CDK7 protein quantitation concluded that CDK7 protein, while elevated in breast cancers relative to normal tissues, was correlated with longer breast cancer specific overall survival." (PMID 32155786, 2020). "This subset of genes encoding transcriptional regulators and signaling factors in HER2-positive cells may partially represent a HER2iR vulnerability, which is mediated by CDK7 in breast cancers." (PMID 31462705, 2020). "This suggests that CDK7 may be an important novel target for breast cancer treatment for all breast cancer subtypes." (PMID 32155786, 2020). "In our study, we found that targeting CDK7 increased the toxic effect of tamoxifen in sensitive and resistant breast cancer cells as well as in vivo models by targeting important proteins, such as ER and MYC, and essential pathways in breast cancer progression (STAT3 and β-catenin)." (PMID 32340192, 2020). "Having found that many of the genes inhibited by THZ1 are regulated in an EGF-dependent manner, we hypothesized that inhibition of CDK7-mediated transcription via THZ1 could potentiate the effects of EGFR inhibition in breast cancer." (PMID 32155786, 2020). "Another study has shown that HER2+ breast cancers may be more sensitive to CDK7 inhibition than ER+ breast cancers and that THZ1 may restore lost sensitivity to HER2-targeting therapies." (PMID 32155786, 2020). "Additionally, high CDK7 expression was correlated with shorter OS in patients with ER+ breast cancer, especially those treated with tamoxifen." (PMID 32340192, 2020). "We confirmed potent inhibition of several off-targets and were keen on reducing the inhibition of FRAP1(mTOR), PIK3CA, and CDK7, as these kinases drive proliferation in breast cancer, which would complicate the interpretation of MELK-dependent pharmacology if inhibited." (PMID 28926338, 2017).
breast carcinoma (continued). "Reasoning that since (a) ER is a transcriptional driver in breast cancer cells, (b) CDK7 activity is required for transcription and (c) CDK7 phosphorylates ER at Ser118, we determined if co-treatment with THZ1 and anti-estrogens would provide additional growth inhibition." (PMID 27748765, 2017). "In addition, CDK7/CDK9 inhibitors have also been evaluated in different stages of clinical trials in breast cancer." (PMID 25990212, 2015). "Furthermore, TNBC cells showed a higher reliance on CDK7 compared to non‐TNBC breast cancer cells." (PMID 39656925, 2025). "Therefore, the use of CDK7 inhibitors in breast cancer may delay the onset of resistance, leading to more sustained responses." (PMID 40949156, 2025). "Furthermore, the question arises as to whether CDK7 expression should be routinely assessed in the treatment of advanced breast cancer with CDK7 small-molecule inhibitors." (PMID 38605321, 2024). "Notably, increased SMC2 expression is associated with poor outcomes in patients with breast cancer, suggesting that modulation of SMC2 by CDK7 or other factors may have significant impact on the aggressiveness of this disease." (PMID 37201585, 2023). "Moreover, CDK7 expression is positively correlated with that of the estrogen receptor (ER) and plays a role in phosphorylating Ser118 on the ER, which promotes ER activity, and CDK7 blockade contributes to reverse endocrine therapy resistance in breast cancer." (PMID 34490348, 2021). "CDK7, a transcriptional CDK exhibiting CDK activating kinase activity on CDK2 and CDK9, has recently been found to be involved in the resistance mechanisms to CDK4/6i in CDK4/6i-resistant ER+/HER2− breast cancer cell models with loss of Rb and exhibiting cyclin E1 overexpression." (PMID 34771560, 2021). "Thus, we hypothesized that GSDME expression elevation is a possible route for CDK7 inhibition to suppress breast cancer cell survival." (PMID 34490348, 2021). "This suggests that CDK7 inhibitors may be effective at treating advanced, ER-mutant breast cancer." (PMID 32385714, 2020). "Furthermore, basal protein expression of one of these genes, CITED2, correlated with THZ1 sensitivity, suggesting that CITED2 may serve as a possible biomarker of response to CDK7 inhibitors in the treatment of all breast cancer subtypes." (PMID 32155786, 2020). "However, bioinformatic analysis indicates that CDK7 RNA expression is associated with negative prognosis in all the major subtypes of breast cancer." (PMID 32155786, 2020). "Thus, we hypothesized that CDK7 contributes to tamoxifen resistance and that CDK7 inhibition can enhance the cytotoxic effect of tamoxifen, particularly in tamoxifen-resistant breast cancer." (PMID 32340192, 2020). "Furthermore, we evaluated the expression of CDK7 in clinical samples from breast cancer patients." (PMID 32340192, 2020). "Thus, the 141-gene set in HER2+ cells may collectively represent a HER2-specific vulnerability, which mediated by CDK7 inhibition in breast cancers." (PMID 31462705, 2020). "It has been suggested that TNBC breast cancers may be uniquely dependent on CDK7." (PMID 32155786, 2020). "CDK7 may also serve as a novel druggable target for multiple subtypes of breast cancer." (PMID 32155786, 2020). "Last, we tested if CDK7 could resensitize HER2iR breast cancer cells to lapatinib in vivo." (PMID 31462705, 2020). "Selective CDK7 inhibitors have demonstrated greater tumor sensitivity than normal cells, driving apoptosis in CDK4/6 inhibitor-resistant breast cancer models." (PMID 39930131, 2025).
breast carcinoma (continued). "Studies indicate that CDK7 activates ER phosphorylation at Ser118, enhancing MYC transcription and mediating tamoxifen resistance in ER+ breast cancer." (PMID 38605321, 2024). "Some other CDK7 inhibitors, for example, SY-1365 and YKL-5-124, show covalent binding to CDK7 and also have low IC50 and positive effects in ovarian and breast cancer, and neuroblastoma, respectively." (PMID 38542080, 2024). "Contrarily, another study demonstrated that elevated CDK7 expression correlated with worse RFS across a broad and unselected cohort of breast cancer patients (n = 3,951), representing multiple subtypes." (PMID 38605321, 2024). "It highlighted that CDK7 protein levels were significantly higher within HR-positive and HER2-positive breast cancer subtypes, as contrasted with the TNBC subtype." (PMID 38605321, 2024). "Intriguingly, recent investigations have illuminated the role of CDK7, whose expression is augmented by AKT in human HER2 inhibitor-resistant breast cancer cells." (PMID 38605321, 2024). "We further explored the role of CDK7 in suppressing nutlin-3 and THZ1-induced breast cancer cell survival." (PMID 36058938, 2022). "Multiple breast cancer cell lines were used to verify the in vitro anti-tumorigenic effect of THZ1, a covalent molecular inhibitor of CDK7." (PMID 36058938, 2022). "CDK7, CDK10, and CDK11 were moderately expressed in normal breast tissues and highly expressed in breast cancer tissues." (PMID 33686962, 2021). "Here, we explored the CDK7 inhibition activity of THZ1 and LDC4297 on MCF-7 and ZR-75-1 breast cancer cells." (PMID 34490348, 2021). "The expression of CDK7 and its cofactors cyclin H and MAT1 was found to be elevated in breast cancer compared with normal breast tissue." (PMID 33686962, 2021). "The results revealed that the mRNA expression of CDK7, CDK8, CDK9, CDK10, CDK12, CDK19, and CDK20 was upregulated in patients with breast cancer." (PMID 33686962, 2021). "We found a significant correlation (rho = 0.41; p = 0.02) between CDK7 and MYC expression in patients with ESR+ breast cancer treated with tamoxifen." (PMID 32340192, 2020). "We found a positive correlation between CDK7 and ER1 mRNA levels in TCGA breast cancer samples (rho = 0.41; p = 0.02) and ER+ breast cancer samples (rho = 0.27; p < 0.001)." (PMID 32340192, 2020). "Here, we provide the first evidence that aberrant activation of SHP2 mediates resistance of breast cancer cells to HER2 blockade and this resistance can be overcome by inhibition of CDK7." (PMID 31462705, 2020). "We then extended this analysis to examine correlations between CDK7 expression and RFS in the following breast cancer subtypes: luminal A, luminal B, basal and HER2 positive." (PMID 32155786, 2020). "This study was the first to show that targeting CDK7 (THZ1 or siRNA) induced tamoxifen cytotoxicity in sensitive and resistant breast cancer cell lines." (PMID 32340192, 2020). "To determine if CDK7 expression levels were predictive of response to CDK7 inhibition, we measured protein and mRNA gene expression levels of CDK7, HER2 and ER in multiple breast cancer cell lines." (PMID 32155786, 2020).